IL6 (interleukin 6)
Diseases named in the same sentence as IL6 in open-access papers (continued):
Sharing a sentence is not in itself a finding about the gene and the disease.
infection (continued). "The presence of the wild-type GG genotype and the G allele for the IL6 -174G/C polymorphism was associated with a 4-fold increased risk for infection and development of TB when comparing individuals with TB and the healthy control." (PMID 37892223, 2023). "It is involved in immunological, infection, inflammatory mechanisms, and polymorphisms in the IL-6 gene region that affect physiological function and other cytokine imbalances." (PMID 37239434, 2023). "G6PD-deficient individuals also produce lower levels of pro-inflammatory cytokines, IL-6, and IL-1β in peripheral mononuclear cells, and their granulocytes display diminished bactericidal activity and increased susceptibility to infection." (PMID 37753082, 2023). "Our previous studies have utilized an influenza A virus and S. pneumoniae coinfection model, and indicated that IL-6 deficiency during an infection results in increased lung cell death." (PMID 35297653, 2022). "Namely, the decreased expression of αvβ3 integrin caused a decrease in the secretion of IL-6 after infection with HAdV26." (PMID 35458402, 2022). "TNF-alpha shares the same characteristics and pharmacokinetics as IL-6, causing a rapid rise 2-4 hours after infection onset." (PMID 35449688, 2022). "In general, Th2 cytokines (e.g., IL-6) and Th17 cytokines (e.g., IL-17A) were associated with infection progression under conditions of compromised immunity, and the differentiation and immune function of Th17 cells was positively regulated by IL-6." (PMID 35558127, 2022). "The infection risk associated with biologic therapies targeting IL-6 or the IL-6 receptor is similar to the risk with TNF inhibitors." (PMID 35214755, 2022). "Infection with HAdV35 caused increased expression of IL-6, IL-1β, TNF-α, and especially IL-8 in both A549 and SK-OV-3 cells." (PMID 35458402, 2022). "Infection experiments in vivo showed that A. baumannii strains expressing high levels of OmpA were more likely to cause bacteraemia in mice; such infections were positively correlated with the level of IL-6 in mouse blood." (PMID 35844614, 2022). "IL-6 is key player in the healthy immune response against infection and blockade of this system is responsible for the increased risk of infection with use of tocilizumab (10% patients per year)." (PMID 36582285, 2022). "IL-6 is a cytokine released by the immune cells and plays a role in the systemic inflammatory changes caused by infection or tissue injury." (PMID 36005726, 2022). "We found that FXR deficiency in hepatocytes promoted the progression of liver injury, aggravated weight loss and death caused by infection, and promoted inflammatory cytokines production, such as IL-6, IL-1β, TNF-α, IL-4, IL-10, and IL-13." (PMID 35930537, 2022). "In summary, serum AST, DBIL LDH, and IL-6 levels are the potential markers for distinguishing severe or critical patients in the early stage of Delta variant infection." (PMID 36052305, 2022). "The improvement of TNF-α, IL-1β, IL-6, and IL-12 have been shown to be associated with the enhanced capacity of macrophages to protect against infections." (PMID 37431006, 2022). "Altogether, this immunological phenotype is consistent with an elevated risk of thrombus formation (IL-6) and with an attempt of the body to decrease the inflammatory response caused by the infection with SARS-CoV-2 (elevated IL-1RA levels)." (PMID 36557244, 2022). "Inhibition of p38 resulted in the recovery of suppressed IL-6 expression, suggesting that the osteosclerotic pattern in combined infections contributes in part to the association between IL-6 and p38 signaling." (PMID 36293485, 2022). "Studies have shown that the expression of inflammatory factors IL-1β and IL-6 in cells is higher than that of fimbriae-deficient strains after infection with wild-type Salmonella." (PMID 36431853, 2022). "The severity of infection is known to be associated with the levels of IL-6 and IL-8, at least to some extent." (PMID 35531475, 2022).
infection (continued). "Murine studies show that knocking out IL-6 makes mice more susceptible to infection with an array of bacteria, viruses, fungi and parasites." (PMID 36203565, 2022). "In summary, serum AST, DBIL, LDH, and IL-6 levels are potential markers for distinguishing severe or critical patients in the early stage of the Delta variant infection." (PMID 36052305, 2022). "Here, we have observed increased IL-6 cytokine levels after primary infection in hamsters with SARS-CoV-2 variants." (PMID 35337002, 2022). "This infection induced the acute production of proinflammatory microglial IL-6 and TNF-α and provoked a chronic loss of microglia." (PMID 35510852, 2022). "The cytokine pattern of EBV-HLH is similar to what we have reported previously while patients with infection-associated HLH caused by other pathogens present higher IL-6 but moderately increased IL-10 and IFN-γ." (PMID 35296096, 2022). "It is known that early cytokines TNF-α and IL-6 are involved in the development of inflammation at the site of infection and cause immune activation and recruitment of macrophages." (PMID 35744668, 2022). "Specificity protein 1 (SP1) is associated with different types of cancer, neurological and cardiovascular disease and ZNF341 is involved in immune-mediated disorders and infection susceptibility by regulating IL-6 signaling." (PMID 36266402, 2022). "The infection of C. perfringens caused a heightened tendency on the concentrations of LPS, IL-6, CRP and PCT (0.05 < P < 0.10), and an increase on the activity of MPO (P < 0.05) in serum of broilers." (PMID 35436978, 2022). "After the neutrophils and monocytes/macrophages migrate to the site of infection, the increased level of pro-inflammatory cytokines (IL-6, IL-8, IL-12, TNF-α, etc.) causes the immunopathology of COVID-19 in the lungs, i.e., the cytokine storm." (PMID 36423150, 2022). "Since the beginning of the pandemic, it was determined in the general population that patients with severe forms of infection exhibit elevated levels of inflammatory cytokines, such as IL-6 and TNF-α, associated with end-organ damage and lethality." (PMID 36016660, 2022). "BM-MSCs infection by ZIKV causes increased IL-6 expression and impaired osteoblast differentiation, pointed out by a decreased expression of alkaline phosphatase (ALP) and Runt-related transcription factor 2 (RUNX2)." (PMID 35887383, 2022). "In this study, relative risk of infection was higher in patients treated with interleukin-1 and interleukin-6 compared with TNFi." (PMID 36034561, 2022). "In acute phare response (APR), IL-6 is reported to be a pro-inflammatory cytokine that increase and determine infection-associated ferritin levels." (PMID 37841828, 2022). "Infection of pregnant mice causes an increase in IL-6 in both maternal serum and fetal brain, and loss of Purkinje cells in lobe VII of the cerebellum." (PMID 35464419, 2022). "The results of the univariate ordinal logistic analysis showed that CRP at Days 4−7 and 8−14, IL‐6 at Days 4−7, and total antibody were significantly associated with the infection severity." (PMID 35759224, 2022). "Some insights in the role of IL-6 are provided by an animal model of influenza virus using IL-6 deficient mice showing that IL-6 ameliorates ALI after infection." (PMID 35930528, 2022). "A small but statistically significant association of IL-6 and C-reactive protein is linked to developing infection-related and -unrelated malignancies." (PMID 35453518, 2022). "In the present study, we demonstrate that selective elimination of IL-6 from B-cells increases susceptibility to TB in terms of the post-infection life span." (PMID 35154093, 2022). "A key question regarding the acute inflammatory response remains: How do macrophages rapidly release the inhibitory effect of let-7 on IL-6 during pathogenic infection." (PMID 36385095, 2022).
infection (continued). "S. aureus USA300 infection caused overexpression of IL‐6, TNF‐α, and IL‐1β in serum, resulted in microglial over‐activation and excessive release of proinflammatory cytokines in the mPFC." (PMID 35977050, 2022). "Infection with HAdV26 caused a 5.7-fold increase in IL-6 gene expression in A549 cells and a 16.7-fold increase in SK-OV-3 cells at 1 h after infection in comparison to non-infected cells." (PMID 35458402, 2022). "C-reactive protein, a nonspecific acute-phase protein produced by hepatocytes in response to IL-6 during inflammation and infection, has also been linked to HF in numerous studies and has been associated with a worse prognosis." (PMID 36014020, 2022). "Serum IL-6 is used as a diagnostic and prognostic biomarker for inflammation, autoimmune disorders, cancer, cardiovascular diseases, and infection." (PMID 35330399, 2022). "Higher levels of these parameters are associated with more severe course of the infection, especially the combination of elevated D-dimer and interleukin-6 levels." (PMID 36430023, 2022). "Massive unregulated release of pro-inflammatory cytokines (cytokine storm) such as tumor necrosis factor-alpha (TNF-α) and interleukin-6 (IL-6) due to infection, nerve injury or immunotherapy causes organ damage and unbearable pain." (PMID 35806192, 2022). "In this work, similar to our previous report, we demonstrated that HPV infection promotes chronic inflammation through high levels of IFN-γ, IL-1β and IL-6 caused by single or multiple infection, and even an increment of IL-4, as in a preliminary study." (PMID 35739948, 2022). "using bone marrow derived DCs showed secretion of IL-6 and IL-12 in response to infection with specific HSV1 KOSTLR2* variants, through either TLR2 or TLR9 stimulation." (PMID 36211447, 2022). "Host immune cells release cytokines such as TNF-α, IL-6, and IL-12 that cause inflammatory signals which recruit more effector cells such as macrophages, neutrophils etc. to site of infection, thereby clearing the pathogen." (PMID 35813825, 2022). "This group of patients had higher levels of IL-6, indicating that the high level of inflammation was caused by infection." (PMID 33746945, 2021). "Among death causes, a higher percentage of infections as cause of death was observed after heart transplant in high IL-6/CXCL10 category." (PMID 33758270, 2021). "This neutrophil cluster formation shortly after infection was diminished in both MZ B cell-deficient mice and IL-6-deficient mice." (PMID 34040603, 2021). "Although interleukins contribute to host defense against infections, exaggerated synthesis of IL-6 can cause an acute severe systemic inflammatory response known as cytokine storm or cytokine-release syndrome." (PMID 33803628, 2021). "Rapid secretions of IL6 are conducive to innate immune response during infection, while the excessive release of IL6 is implicated in the course of inflammatory disorders." (PMID 35095505, 2021). "Increased IL-6 levels are an important hallmark of the cytokine storm, which is produced in response to infection and tissue damage." (PMID 34539644, 2021). "It has been described that the overproduction of IL-6 after infection with Group B Streptococcus is associated with iNOS expression." (PMID 34987496, 2021). "Among the L. pneumophila-induced cytokines impacted by TLR3 and/or TLR4, IL-6 and IL-1β are associated with increased neutrophil infiltration to sites of infection." (PMID 34280250, 2021). "Chromatin accessibility for pro-inflammatory and infection-associated genes such as Il1b, Il6, Nlrp3, Itgam (Cd11b), CD80, CD14, Fos, and Jun were also increased in infected AMs and IMs (cluster 5)." (PMID 34292313, 2021). "A higher level of IL-6 has also been shown to play an important role in infection-associated inflammation." (PMID 34829902, 2021).
infection (continued). "In the course of acute inflammation caused by trauma, surgery, stress reaction, and infection, IL-6 will be produced rapidly, which leads to the increase of serum IL-6 level, which can be used as early warning indicator." (PMID 34659832, 2021). "IL-6 and IL-12p40 production from microglia were both highly upregulated during infection with T. gondii, but CXCR3 deficiency significantly decreased the concentrations of these cytokines by 54% and 42%, respectively." (PMID 34835465, 2021). "In numerous in vitro and in vivo studies, proinflammatory signals, such as TNF-α, IL-1β, and IL-6, have been implicated in deviating immune responses to infection with S. aureus and E. coli." (PMID 34222051, 2021). "In our study, only infection in old RMs caused an increase in the proportion of IL-6-secreting cells in lung tissue, accompanied by an increase in the activation level of NF-κB in ACE2+ cells, and enhanced STAT3 and NF-κB activation in ACE2- cells." (PMID 34471088, 2021). "Our data also showed that the infection with high virulent and pathogenic strains led to reduced expression of IL-6 and IL-12." (PMID 34336720, 2021). "A significant increase in the release of IL-6 and IL-8 was observed after 3 and 5 h of infection with the purified FliC protein, and a decrease in IL-6 and IL-8 release was observed after 3 h of infection with the strain containing a mutation in the fliC gene." (PMID 34835359, 2021). "In this experimental condition, infection was associated with exacerbated inflammatory response, including increased circulating levels of TNFa, IL-6, and IL-1beta." (PMID 35008695, 2021). "During infection and inflammation, cytokines, including IL-6, increase the hepcidin synthesis and cause iron sequestration in macrophages." (PMID 33994996, 2021). "During infection, the expression of IL-1β, IL-6, TNF-α, and iNOS in the Glu deficiency group was significantly decreased compared with the APEC XM infection group." (PMID 34502151, 2021). "Rapid production of IL-6 contributes to host defense during infection and tissue injury, but excessive IL-6 production causes severe inflammatory diseases." (PMID 34327146, 2021). "IL-6 is deemed a specific indicator of infection-associated preterm labour and peripheral increases, as well as at the maternal–fetal interface and within the amniotic and cervicovaginal fluid is deemed a risk factor for preterm birth." (PMID 33980919, 2021). "The overproduction of pro-inflammatory cytokines such as TNF-a and IL-6 plays an important role in the infection caused by S. suis." (PMID 34357984, 2021). "Interleukin (IL)-6 and IL-12 are crucial cytokines for immune-mediated resistance to T. cruzi, as shown either by infection of genetically deficient mice or in vivo cytokine neutralization." (PMID 35095849, 2021). "CYP3A4 rs2242480C>T, SLC22A11 (OAT4) rs11231809T>A, TLR2 rs4696480T>A, and IL6 rs1800796C>G genetic polymorphisms are associated with the incidence of infections among patients undergoing cytotoxic chemotherapy." (PMID 33776761, 2021). "What’s more, either SARS-CoV-2 or it’s variants infection, Meplazumab treatment had a favorable therapeutic effect on the downregulation of cytokines and chemokines at 6 d.p.i., such as IL-6, IL10, IL1b, CCL2, CXCL1, CXCL2, IFN-γ, IL-17, and CyPA." (PMID 34564690, 2021). "IL-6 can be secreted by T cells and macrophages, causing an immune response during infection or after injury and ultimately leading to inflammation of the gastric mucosa or other tissues." (PMID 34471638, 2021). "The upregulation of TNFα, IL6, IL1β, and IFNγ was reported as inflammatory cytokines associated with the postviral infection, which played a role in the recruitment of more immune cells for defense against the virus." (PMID 34074129, 2021).
infection (continued). "Other factors such as smoking, viruses, and a person’s disease can cause the increase of IL-6, IL-8 and IL-10 in the patient’s body., Our research cannot completely rule out the influence of these factors and other undiagnosed infections." (PMID 34925324, 2021). "Pathway analysis identified toll-like receptor (TLR) activation as the likely underlying signalling pathway discriminating infection from a common background of IL-6 pathway mediated neuroinflammation." (PMID 33409494, 2020). "In mammals, IL-6 is a pivotal modulator of the response to tissue damage caused by infection and disease, as it functions as both a proinflammatory and anti-inflammatory cytokine." (PMID 32273831, 2020). "We here confirmed that both, TNFα and IL-6 were markedly increased in CIA mice after infection and this was accompanied by severe bone loss within a few days of SA progression." (PMID 33117382, 2020). "Anti-inflammatory therapies such as anti-IL-6 therapy have the potential to impair viral clearance, pre-dispose to secondary infection, and cause harm." (PMID 33195334, 2020). "Further, elevated serum IL-6 levels have been implicated as a potential biomarker for disease severity in pH1N1-alone infections." (PMID 33202895, 2020). "Accordingly, IL-6-/- mice are susceptible to a systemic infection with high doses of intravenously (i.v.)delivered Mtb." (PMID 33334075, 2020). "The predominant cytokine that was increased was IL-6, a marker of infection associated PTL, which has been previously shown to be significantly increased in amnion in women who deliver preterm compared to term." (PMID 32983111, 2020). "IL-6 is a functionally pleiotropic cytokine implicated in inflammation and infection responses as well as the regulation of metabolic and neural processes." (PMID 32878032, 2020). "The side effects of existing treatments targeting IL-6 signaling in humans are believed to result from a blockade of classic signaling, resulting in an increased susceptibility to infections, due to the key role of IL-6 signaling in responding to infection." (PMID 32765502, 2020). "So far, autoantibodies to interferon (IFN)-γ, GM-CSF, to a group of TH-17 cytokines comprising IL-17A, IL-17F, IL-22, IL-23, and to IL-6 have been found to be causative or closely associated with susceptibility to infection." (PMID 32419033, 2020). "In conclusion, our findings revealed that IL-6 enhances type 1 cytokine responses and the recruitment of immune cells during the early stage of infection, two events that are critically associated with the control of Brucella infection." (PMID 33322581, 2020). "So far, autoantibodies to interferon (IFN)-γ, GM-CSF, to a group of TH-17 cytokines and to IL-6 have been found to be causative or closely associated with susceptibility to infection." (PMID 32419033, 2020). "Pathway analysis provided a biologically plausible explanation of differential upstream initiation in infection by TLR signalling via IL-17 in addition to common IL-6 associated inflammation in sterile neuroinflammation." (PMID 33409494, 2020). "Iatrogenic, acquired, and inherited defects have provided evidence of the consequences of impaired IL-6 signaling through their impact on infection susceptibility." (PMID 32308976, 2020). "(ii) Immunologic sounding: Persistent local infection caused by P. gingivalis induces the upregulation of inflammatory cascades involving IL-1, IL-6, IL-8, TNF-α, CRP, and IFN." (PMID 33202751, 2020). "Here, we have showed that IL-6 KO mice were more susceptible to Brucella infection than wild-type animals during the acute phase of the infection." (PMID 33322581, 2020). "Individuals with diabetes, a history of recurrent infection, age ≥65, and corticosteroid use have been shown to be at an increased risk of developing a more serious infection following IL‐6 inhibitor use." (PMID 32681537, 2020).